RNU6-233P (RNA, U6 small nuclear 233, pseudogene)
Gene: Small nuclear RNA gene on chromosome 17 (39,546,104 to 39,546,244, reverse strand). Ensembl gene ENSG00000222777.
Homologues: Orthologues: chimpanzee U6 (99% identical), guinea pig U6 (55% identical). Paralogues in human: RNU6-694P (62% identical), RNU6-884P (57% identical), RNU6-1094P (57% identical), RNU6-1243P (57% identical), RNU6-24P (57% identical), RNU6-403P (57% identical), RNU6-43P (57% identical), RNU6-454P (57% identical), RNU6-727P (57% identical), RNU6-1091P (56% identical), RNU6-115P (56% identical), RNU6-1309P (56% identical), and 1284 more.